USP8 (ubiquitin specific peptidase 8)
Diseases named in the same sentence as USP8 in open-access papers (continued):
Sharing a sentence is not in itself a finding about the gene and the disease.
tumor (104 papers, 2016 to 2026). "Retrospective Sanger sequencing of the initial tumor identified a USP8 c.2159C>G p.(Pro720Arg) mutation, a common variant in CD." (PMID 41971637, 2026). "Our results highlight the role of biomechanical signaling in ECM-induced tumor progression and immune evasion of PCa and the underlying therapeutic value of USP8 inhibition in immunotherapy sensitization." (PMID 40410130, 2025). "WES demonstrated a loss-of-function variant in the G-protein coupled receptor 162 [GPR162 (R218*)] in the right corticotroph tumor, and a novel missense variant in ubiquitin specific peptidase 8 [USP8 (P681Q)] in the left tumor." (PMID 40544420, 2025). "In these malignancies, elevated USP8 levels are associated with tumor progression, metastatic potential, higher recurrence rates, and unfavorable clinical outcomes." (PMID 41301681, 2025). "USP48 mutations are found in a subset of USP8-wild-type tumors and are associated with a smaller tumor size and preserved feedback responsiveness to suppressive factors, but their clinical implications are still unclear." (PMID 40364036, 2025). "Somatic USP8 pathogenic variants correlate with worse tumor behavior and patient outcomes in pediatric-onset CD." (PMID 40813536, 2025). "The novel USP8 variant (P681Q) found in the contra-lateral tumor led to increased POMC transcription similar to the well characterized USP8 hotspot variant S718P." (PMID 40386408, 2025). "The novel USP8 variant (P681Q) found in the contra-lateral tumor led to increased POMC transcription although weaker than the well characterized hotspot variant S718P, and did not affect EGFR ubiquitin." (PMID 40544420, 2025). "We now describe a novel missense USP8 variant c.1724C > A in the left tumor of our patient which when overexpressed, resulted in increased POMC transcription, comparable to that observed with the hotspot USP8 mutation S718P." (PMID 40386408, 2025). "The contra-lateral (left) corticotroph tumor from our patient harbored a novel USP8 c.1724C > A variant which causes a missense P681Q with 18.7% VAF (of 187 reads), which was further validated by amplicon NGS sequencing (23.8% VAF, 146 out of 614 reads)." (PMID 40386408, 2025). "GFP-tagged EGFR in combination with Myc-tagged USP8-WT, USP8-P681Q, and the USP8-S718P variant as well as empty vector were transiently transfected into corticotroph tumor cells followed by immunoprecipitation with anti-GFP antibody linked agarose beads." (PMID 40544420, 2025). "Collectively, the available data suggest that USP48 mutations contribute to CD’s pathogenesis and are a common mutation in USP8-wild-type CD, associated with a smaller tumor size and a tendency towards the female gender." (PMID 40364036, 2025). "A more recent study aimed to investigate the impact of USP8 variants on in vitro response to Pasirotide in primary cultures obtained from 7 FCAs and also in murine corticotroph tumor cells." (PMID 38862897, 2024). "The data on the association of USP8 variants with clinical manifestations of CD and tumor growth are controversial." (PMID 39684597, 2024). "Data regarding sex, age, hormonal level, tumor size, and clinical outcomes in USP8-mutated individuals with FCA are relatively consistent among different studies." (PMID 38862897, 2024). "The USP8 variant was found in c.2159 C > G (p.Pro720Arg) and was positively correlated to the tumor size." (PMID 38862897, 2024). "USP8 inhibitor resulted in decreased tumor formation, and mice with Usp8 deficiency showed improved survival rates." (PMID 38638430, 2024). "In summary, these findings indicated that increased USP8 expression was strongly associated with tumor malignancies and a worse prognosis." (PMID 38973004, 2024).
tumor (continued). "USP8-mutated tumors exhibited nonaggressive behavior as four out of five tumors were microadenomas and only one USP8-mutated tumor developed metastasis, which responded well to therapy." (PMID 36968144, 2023). "Reincke and colleagues revealed frequent somatic hotspot gain-of-function mutations (GOF) in the gene encoding for USP8, especially in female adult patients diagnosed at a younger age with a smaller tumor size." (PMID 37109772, 2023). "These mutations are generally related to smaller tumor size and less aggressive growth USP8-mutatated and wild type tumors are also characterized by different biological features." (PMID 37065760, 2023). "In this study, we demonstrated that in pancreatic tumor cell lines, USP8 deficiency induced a time and dose-dependent decrease in the PD-L1 protein level and increased the amount and function of tumor-infiltrated activated T-cells." (PMID 36539510, 2023). "The report detected that tumours with USP8 and GNAS mutations have distinct transcriptomic profiles compared to tumours without these tumour driver variants, indicating that transcriptomic studies can bring valuable information on PitNET functional aspects." (PMID 36774501, 2023). "Clinically, the expression of USP8 showed a significant association with the tumor-node-metastasis stage in multiple patient-derived cohorts of pancreatic cancer." (PMID 36539510, 2023). "Overall, the mechanism by which USP8 reduces cisplatin activity is linked to a change in tumor cell susceptibility to apoptosis." (PMID 36578788, 2022). "Here, we studied the impact of USP8 mutations on pasireotide responsiveness in human and murine corticotroph tumor cells." (PMID 35626057, 2022). "A ubiquitin-specific peptidase 8 (USP8) somatic pathogenic variant (c.2159C>G/p.Pro720Arg) was found in the tumor." (PMID 35029852, 2022). "We then evaluated the impact of USP8 mutations on the in vitro responsiveness to pasireotide in corticotroph tumor cells." (PMID 35626057, 2022). "In this study, we uncover a molecular mechanism that USP8 regulates PD-L1 K63-linked ubiquitination and immune response signaling pathways to control anti-tumor immunity." (PMID 35361799, 2022). "Although the availability of a small number of primary cultures and the use of only one P720R USP8-mutated tumor are major limitations of our study, data obtained in AtT-20 cells are strongly encouraging and seem to support these evidences." (PMID 35626057, 2022). "Pasireotide failed to reduce ACTH secretion in primary cells from one S718P USP8-mutated tumor but exerted a strong antisecretory effect in primary cells from one P720R USP8-mutated tumor." (PMID 35626057, 2022). "ACTH-secreting tumours in men are less likely to harbour somatic USP8 mutations that are linked to smaller and less invasive tumours." (PMID 36018781, 2022). "This study investigated the impact of USP8 mutations on corticotroph tumor cells responsiveness to the treatment with the somatostatin analog pasireotide." (PMID 35626057, 2022). "Approximately 40% of patients have mutations in USP8 or USP48 genes that have a strong effect on tumor biology, including changes in the expression of cell cycle-related genes." (PMID 36428684, 2022). "Our clinical data are in line with those of Martins and colleagues, showing that USP8 mutated tumors have a superior tumor size but a similar clinical and biochemical phenotype to wild-type tumors." (PMID 34439178, 2021). "In vitro functional studies of the new USP8 G664R variant were performed in mouse corticotroph tumor cells AtT-20, bearing wild-type USP8 and endogenously expressing EGFR." (PMID 34439178, 2021). "Because USP48 mutations affect the processes of protein degradation similarly to mutations of USP8, we screened the tumor samples for both the mutations." (PMID 33498176, 2021).
tumor (continued). "In cervical squamous cell carcinoma, USP8 expression is increased in tumors compared to adjacent normal tissues, and its expression is associated with high recurrence risk and an advanced tumor stage." (PMID 34577547, 2021). "Functional characterization of USP8 G664R variant was performed in murine corticotroph tumor AtT-20 cells." (PMID 34439178, 2021). "The studies showed that USP8 mutation is related to lower tumor size and clinical remission after surgery." (PMID 33498176, 2021). "In adrenocorticotropic hormone (ACTH)-secreting pituitary adenomas, USP8 mutations were found to be a main tumor-driving cause plus highly specific for this type of PitNET." (PMID 32498309, 2020). "In this USP8-mutated tumor, we identified an interesting somatic mutation in the gene RASD1, which is a component of the corticotropin-releasing hormone receptor signaling system." (PMID 28487882, 2017). "The reason for this apparent discrepancy was the fact that increased nuclear USP8 was associated with a smaller size of the tumours (Spearman r = - 0.52, p = 0.005**)." (PMID 28005997, 2016). "Furthermore, both the USP8 P618Q mutation identified in our patient and the hotspot S718P variants increased murine corticotroph tumor cell proliferation (USP8 P618Q vs. USP8 S718P fold change: 1.12 ± 0.03 vs. 1.14 ± 0.07, p < 0.05)." (PMID 40386408, 2025). "In summary, we report for the first time a double pituitary corticotroph tumor which harbored a G-protein coupled receptor (GP162) variant in one tumor and a novel ubiquitin specific protease (USP8) variant in the second corticotroph tumor in the setting of a background germline CYP21A2 variant." (PMID 40386408, 2025). "Beyond their implications for tumor behavior and invasiveness, recent studies found that USP8 mutations might also have implications for pharmacologic treatment responsiveness." (PMID 40364036, 2025). "Overexpression of the USP8 P681Q variant that we had found in our patient in murine corticotroph tumor cells caused an increase in POMC mRNA expression which was comparable to the USP8 hotspot S718P mutation (USP8 P618Q vs. USP8 S718P fold change: 1.26 ± 0.014 vs. 1.31 ± 0.11)." (PMID 40386408, 2025). "GFP-tagged EGFR in combination with Myc-tagged WT-USP8, USP8-P681Q variant, and the USP8-S718P variant as well as empty vector were transiently transfected into corticotroph tumor cells followed by immunoprecipitation with anti-GFP antibody linked agarose beads." (PMID 40386408, 2025). "For corticotroph tumors with quiet genomes, consider somatic mutation analysis, as it may have therapeutic implications (e.g., USP8-mutated tumor tends to respond better to pasireotide)." (PMID 39441837, 2025). "In summary, we report for the first time a double pituitary corticotroph tumor which harbored a G-protein coupled receptor (GPR162) variant in one tumor and a novel ubiquitin specific protease (USP8) variant in the second corticotroph tumor in the setting of a background germline CYP21A2 variant." (PMID 40544420, 2025). "It remains unknown how USP8 mutations affect the regulation of tumor growth and the severity of disease." (PMID 39684597, 2024). "Moreover, a cohort of 60 patients with FCA indicated smaller tumor size and less invasiveness in USP8-mutated tumors." (PMID 38862897, 2024). "There are also some discrepancies on tumor size and invasiveness in USP8-mutated tumors." (PMID 38862897, 2024). "Furthermore, USP8 inhibition and USP8 deficiency significantly improved activated tumor cell killing mediated by T cells in vitro." (PMID 36539510, 2023). "An isolated USP8 mutation alone cannot fully explain the entire behavior of the tumor." (PMID 38023185, 2023).
tumor (continued). "Moreover, we found that USP8 deficiency inhibited pancreatic tumor proliferation and extended overall survival by improving anti-tumor immunogenicity." (PMID 36539510, 2023). "However, USP8 expression was demonstrated to be associated significantly with the tumor-node-metastasis (TNM) stage in a clinical association study in various patient-derived pancreatic cancer cohorts (p = 0.041)." (PMID 36539510, 2023). "Meanwhile, USP8 deficiency could reduce tumor invasion and migration and tumor size in an immunity-dependent manner, and improve anti-tumor immunogenicity." (PMID 36539510, 2023). "They clearly show a trend in which higher receptor expression corresponds to more favorable clinical profile in patients, including lower plasma ACTH level, smaller tumor size, clinical remission after surgery and favorable features of sparsely granulated, USP8-mutated tumors." (PMID 37065760, 2023). "Furthermore, Traf6 deficiency almost abolished the Usp8-deficient CT26 tumors sensitization to anti-PD-L1 immunotherapy in syngeneic mouse tumor model." (PMID 35361799, 2022). "The expression levels of four genes related to cell-cycle regulation were determined with qRT-PCR in tumor tissue from 70 patients with corticotroph tumors including patients with USP8 mutations (n = 20), USP48 mutations (n = 5) and wild-type patients (n = 42)." (PMID 36428684, 2022). "Moreover, PD-L1 expression, MHC-I and the infiltrated CD8+ cytotoxic T cells were significantly upregulated in Usp8-deficient tumor tissues treated with control IgG or anti-PD-L1 antibody." (PMID 35361799, 2022). "In conclusion, P720R USP8 mutation might be considered as a molecular predictor of favourable response to pasireotide in corticotroph tumor cells." (PMID 35626057, 2022). "This tumor and the ACTH-CA were the only two neoplasms that harbored a USP8 variant." (PMID 35563252, 2022). "To better characterize the impact of USP8 mutations on pasireotide-mediated regulation of cell cycle, we tested cyclin D3 expression in primary cultured cells from two wild-type USP8 tumors (#1 and #2) and one P720R USP8-mutated tumor (#7) exposed to pasireotide for 4 h." (PMID 35626057, 2022). "However, p-p65, MHC-I and tumor-infiltrating CD8+ cytotoxic T cells were significantly elevated in Pd-l1-deficient CT26 tumor tissues treated with the USP8 inhibitor alone or combination compared with the control group." (PMID 35361799, 2022). "In both cell lines USP8 silencing resulted in increased susceptibility to cisplatin-induced apoptosis in keeping with the hypothesized general role of this DUB in tumor cell survival independently of the relative resistance to cisplatin." (PMID 36578788, 2022). "Our study is the first of its kind, as it determined the role of lncRNA SNHG12 as a predictor of prognosis and clinicopathologic features of patients with NSCLC and its ability to promote the immune escape of NSCLC and tumor growth when linked with the HuR/PD-L1/USP8 axis." (PMID 35658874, 2022). "The USP8 variant positively correlated with increased tumor mass (p = 0.019)." (PMID 35563252, 2022). "In patients with Cushing’s disease, these mutations appear related to lower tumor size and clinical remission after surgery, which could allow to consider USP8 mutations a possible favorable prognosis marker." (PMID 33498176, 2021). "However, elevated nuclear USP8 protein expression in a subset of tumours was associated with a similar phenotype as in their human counterparts, indicating a possible end-point convergence of the different genetic backgrounds in the two species." (PMID 28005997, 2016). "In this study, we aimed to verify whether USP8 mutations also play a role in the development of such tumours in dogs." (PMID 28005997, 2016).
tumor (continued). "Furthermore, we identified USP8 is a novel DUB of GPR34, which could rescue the effects caused by GPR34 deletion, and targeting USP8 with DUB-IN-3 could restrain tumor growth in ATC, offering a new potential strategy for this treatment-resistant cancer." (PMID 40862294, 2025). "We assume that USP8 mutation-associated dysregulations of Wnt signaling may result in alterations in SST2/5 receptors’ trafficking causing alterations in molecular mechanisms that control tumor growth and progression." (PMID 39684597, 2024). "Importantly, the heterogeneity of the USP8 clinical phenotype after transsphenoidal surgery could be attributed to the fact that the tumor size was generally associated with the clinical remission." (PMID 37109772, 2023). "However, the major driver mutations in USP8 wild-type tumours remain elusive." (PMID 33515368, 2021). "Also, even in USP8-mutant tumors, a possibility may exist of additional contributing mutations, following a paradigm from other neoplasm types where multiple somatic alterations contribute to neoplastic transformation." (PMID 28487882, 2017). "Immunohistochemistry of tumor specimens showed that overexpression of YAP partially rescued the reduced expression of YAP and Ki67 caused by USP8 depletion." (PMID 41565619, 2026). "Targeted modulation of USP8 not only inhibits tumor progression but also enhances sensitivity to anti-tumor agents." (PMID 40607251, 2025). "Tumor growth in the sh-USP8 group was significantly slower than that in the control group, and tumor growth in the USP8 overexpression group was significantly faster than that in the control group." (PMID 40410130, 2025). "The tumor weights and volumes were smaller in the sh-USP8 group than that in the control group, and the tumor weights and volumes were increased in the USP8 overexpression group than that in the control group." (PMID 40410130, 2025). "Pretreatment with USP8 inhibitors reduces tumorigenesis, and USP8-knockdown tumor models in immunocompetent mice demonstrate significantly prolonged survival." (PMID 41301681, 2025). "In tumor tissues of other organ systems (including lung, gastric, and pancreatic cancers), USP8 functions as a tumor suppressor." (PMID 40607251, 2025). "Mice implanted with RM-1 cells with simultaneous USP8 knockdown and NBR1 overexpression showed higher tumor growth rates compared with those bearing USP8-silencing cells." (PMID 40410130, 2025). "Rescue experiments confirmed that OGT overexpression reversed the anti-tumor effects of USP8 knockdown, solidifying the USP8–OGT axis as a core driver of iCCA." (PMID 41301681, 2025). "siUSP7, siUSP8, siUSP14 and siUSP19 lead to the largest reduction in TOM22, which means induction of mitophagy and anti-tumor effect, but USP8 and USP19 are low expressed in tumor." (PMID 40316942, 2025). "Functionally, USP8 depletion suppresses tumor invasion, migration, and volume in an immune system-dependent manner, while enhancing anti-tumor immunogenicity." (PMID 41301681, 2025). "One of our studies indicated that USP8 stabilizes β-catenin through deubiquitination, thereby promoting the growth, invasion, tumor stem-like characteristics, and ferroptosis resistance of HCC63." (PMID 40607251, 2025). "We now describe a novel missense USP8 variant c.1724 C > A in the left tumor of our patient which when overexpressed, resulted in increased POMC transcription, but weaker than that observed with the hotspot USP8 mutation S718P." (PMID 40544420, 2025). "A combined approach using USP8 and PD-L1 inhibitors has the potential to reduce tumor growth and increase the effectiveness of CD8+ T-cell-mediated cancer cell destruction." (PMID 38474186, 2024). "Then, protein mass spectrometry was performed to investigate the deep mechanism of USP8 in the tumor." (PMID 38973004, 2024).